MYH6 (myosin heavy chain 6)
Diseases named in the same sentence as MYH6 in open-access papers (continued):
Sharing a sentence is not in itself a finding about the gene and the disease.
hypertrophic cardiomyopathy (continued). "Our data have been supported by published reports in experimental animals in which MYH6 levels were significantly upregulated concurrently with the induced tachycardia and the left ventricular hypertrophy in mutant mice with familial hypertrophic cardiomyopathy." (PMID 25750702, 2015). "The present results showed that many genes significantly altered in cell development and hypertrophic cardiomyopathy by overexpressed atrogin-1, Myh6, Serca2 (ATP2A2) and Prkcz were significantly up-regulated, whereas Itga3 (also known as CD49c) and Foxa2 were down-regulated.." (PMID 23335977, 2013). "There are close correlations between MYH6 variants and congenital heart defects (CHDs), nonsyndromic coarctation of the aorta, familial dilated cardiomyopathy, ischemic cardiomyopathy, and hypertrophic cardiomyopathy." (PMID 37701139, 2023). "In patients with hypertrophic cardiomyopathy, an increase in β‐myosin heavy chain expression, that is, a higher MYH7 to MYH6 ratio, is commonly observed." (PMID 39981966, 2025). "However, hypertrophic cardiomyopathy resulting from HRas mutation associated with chronic constitutively activated Ras/Raf/MEK/ERK pathway and pathological hypertrophy leads to apoptosis, similar to the phenotype seen in TetO-HRas; Myh6-tTA mice used in this study." (PMID 36337898, 2022). "The results showed that genes (DES, MYH6, MYL2, MYL3, TPM1, TPM3, TPM4, and TTN) in MCODE 2 were significantly involved in dilated cardiomyopathy and hypertrophic cardiomyopathy (HCM)." (PMID 35645614, 2022). "Although there is no exact proportion of people with hypertrophic cardiomyopathy, patients with MYH7 R453C mutation have been reported as an inherited familial HCM worldwide while HCM patients carrying the MYH6 R453C variant were rare." (PMID 38862020, 2024). "Therefore, we hypothesized that MYH6 might play key roles in ICM via regulating signaling pathway of cardiac muscle contraction, hypertrophic cardiomyopathy and dilated cardiomyopathy." (PMID 32631246, 2020).
atrial septal defect (31 papers, 2009 to 2025). Interauricular communication is a congenital malformation characterized by a communication between the atrial chambers of the heart. "In recent years, pathogenetic variants on the MYH6 gene have also been correlated with atrial septal defects and hypoplastic left heart syndrome." (PMID 40004541, 2025). "Genetic mutations in cardiac transcription factor genes such as NKX2-5, GATA4, TBX5 and MYH6, located in chromosome 14q12, have been associated with atrial septal defects." (PMID 40843896, 2025). "Myh6 is a cardiac muscle myosin that is preferentially expressed in the atrial chambers and its mutation causes atrial septal defect." (PMID 38110334, 2023). "MYH6 plays a pivotal role in the development of the atrial septum, and MYH6 variation is associated with atrial septal defect (ASD)." (PMID 36721086, 2023). "MYH6 encodes alpha‐cardiac myosin heavy chain, and mutations in MYH6 result in familial atrial septal defects and congenital heart defects." (PMID 33410284, 2021). "Mutations in MYH6 that cause atrial septal defect appear to affect the interaction between the myosin heavy chain and the RLC or between myosin and actin." (PMID 34634306, 2021). "Most cases of WPW have been linked to pathogenic variants in PRKAG2 or MYH6, glycogen storage disorders, mitochondrial syndromes, or congenital heart diseases such as septal defects, Ebstein malformation of the tricuspid valve, or HCM." (PMID 33797204, 2021). "MYH6 mutations in humans have been associated with congenital heart defects such as atrial septal defect, as well as in hypertrophic and dilated cardiomyopathy." (PMID 30975218, 2019). "In line with the BAV association of p.Arg721Trp in MYH6, rs7543130, and rs1830321, all three variants associate with ventricular defects and/or atrial septal defects (P < 0.006)." (PMID 29511194, 2018). "This protein is encoded by the MYH6 gene and is associated with atrial septal defects, late-onset hypertrophic cardiomyopathy and sick sinus syndrome due to mutations." (PMID 28692647, 2017). "Myosin heavy chain 6 (MYH6) mutations have been identified as another cause of atrial septal defects." (PMID 21532774, 2010). "These genes are known to be required fornormal heart function in humans, with mutations in MYH6 andMYH7 implicated in atrial-septal defects and familialhypertrophic cardiomyopathies respectively (Chinget al., 2005; Geisterfer-Lowrance etal., 1990)." (PMID 19769958, 2009). "The majority of cases are sporadic, but some are inherited and associated with mutations in specific genes such as NKX2-5 (also associated with atrioventricular conduction defects), GATA4, TBX5 (associated with Holt–Oram syndrome) and MYH6 (implied in septal defects)." (PMID 40843896, 2025). "Similarly, in the case of atrial-septal defects caused by MYH6 mutations, changes in myosin-based force production affect cardiac development." (PMID 34634306, 2021). "As previously stated, MYH6 has been associated with atrial septal defects, but may also have a role in hypoplastic left heart, ventricular septal defects, and other cardiac malformations." (PMID 29368431, 2018). "Similarly, rare missense mutations in MYH6 gene (cardiac muscle protein-coding gene) can cause sporadic atrial septal defects." (PMID 25435801, 2014). "MYH6 mutations have been associated with atrial septal defects (ASD) and recently were shown to be significantly associated with CoA in a GWAS study of an Icelandic population." (PMID 31888141, 2019). "Segregation studies on dominant MYH6 and MYH7 mutations linked to congenital heart defects (CHDs) such as atrial septal defects have demonstrated variable penetrance, with several mutation carriers exhibiting no structural heart abnormalities." (PMID 40004541, 2025). "The genes in this cluster included Nkx2-5, Myh6, Tbx5, and ten others, which were preferentially related to the CHDs like atrial septal defect (ASD) and ventricular septal defect (VSD)." (PMID 36575170, 2022).
atrial septal defect (continued). "Mutations in MYH6 MHC, the primary atrial myosin isoform, can lead to atrial septal defect, a congenital heart malformation." (PMID 34634306, 2021). "The mutations in various genes have been associated with atrial septal defects, for instance, mutations in NKX2–5, GATA4, TBX5, and MYH6." (PMID 29969989, 2018). "To date, several diseases associated with MYH6 mutations such as hypertrophic (HCM), dilated cardiomyopathy (DCM) and atrial septal defect (ASD) have been reported." (PMID 29969989, 2018). "Consistent with this, also mutations in MYH6, a specific target of GATA4 and TBX5, have been associated with atrial septal defects." (PMID 25435801, 2014). "Notably, a recent report described a 5-month-old boy with an atrial septal defect and a deletion encompassing MYH6 exons 1–26 and MYH7 exons 28–40." (PMID 40004541, 2025). "In our study, although one 11-year-old boy (SGZ-43A) had atrial septal defect, he did not have MYH6 variants." (PMID 36721086, 2023). "There are various types of ASD; ASD type III — sinus venosus atrial septal defect— is caused by mutations in MYH6." (PMID 29969989, 2018). "For example, in the case of atrial septal defect (ASD) and ventricular septal defect (VSD), candidate genes can be counted: NKX2-5, GATA4, TBX20, MYH6, and TBX5, while the pathogenesis of atrioventricular septal defect (AVSD) involves genes, such as PTPN11, KRAS, SOS1, RAF1, and CRELD1." (PMID 34946970, 2021).
dilated cardiomyopathy (25 papers, 2016 to 2025). Cardiomyopathy which is characterized by dilation and contractile dysfunction of the left and right ventricles. "Specifically, MYH6 mutations have been linked to both hypertrophic and dilated cardiomyopathies, with distinct cases exhibiting a transition from a hypercontractile state to myocardial thinning and ventricular dilation." (PMID 40004541, 2025). "It has been reported that mutations of MYH6 associated with hypertrophic and dilated cardiomyopathy." (PMID 32631246, 2020). "Mutations in the MYH6 gene are associated with hypertrophic as well as dilated cardiomyopathy, frequently associated with DMD." (PMID 32927262, 2020). "One explanation might be that this was a parallel change to adapt to the changes associated with dilated cardiomyopathy and other pathological phenotypes seen in MYH6-Cre-BDNF–/– hearts, which require more gene activation to compensate for the ablation of BDNF in cardiomyocytes." (PMID 36061561, 2022). "First, three Hub genes (MYH6, ASPN, and COL14A1) associated with dilated cardiomyopathy-related HF were identified using a large-scale training dataset." (PMID 41158506, 2025). "Variants of uncertain significance (VUS) were found in 17 cases (eight resuscitated and nine dead) in genes associated with HCM or dilated cardiomyopathy (DCM), such as TTN, TNNT2, MYH6, DSP, ACTN2, CALR3, and MYH7." (PMID 36588553, 2022). "While using the Myh6-Cre, expressed at embryonic day 10.5 and upregulated during fetal and postnatal cardiac development, to inactivate Yap, death occurred only when the mice were 11 to 20-week-old, with dilated cardiomyopathy." (PMID 30811446, 2019). "In addition, MYH6 variants are implicated in a wide spectrum of congenital heart malformations, including hypoplastic left heart syndrome (HLHS), Shone complex, ostium secundum atrial septal defects, atrial fibrillation, and dilated cardiomyopathy." (PMID 38370698, 2024). "For example, decreased MYL2 and MYH6 gene expression coincided with increased RYR2, HCN4, CORIN, NPPA, ERBB2, and MYH7 gene expression in hypertrophic and/or dilated cardiomyopathy." (PMID 32804947, 2020). "Collectively, these results suggest that in the context of end-stage dilated cardiomyopathy, the transcriptional regulation of MYH6 and MYH7 is uniformly affected, independent of factors such as age or sex." (PMID 41295372, 2025). "MYH6, ASPN, and COL14A1 may be potential biomarkers for HF in dilated cardiomyopathy." (PMID 41158506, 2025).
myocarditis (16 papers, 2015 to 2025). Myocarditis is a condition that is characterized by inflammation of the heart muscle (myocardium). "In accordance with the mechanistic role of autoantigens in ICI myocarditis, two studies identified α-myosin (encoded by MYH6 gene) as a self-antigen targeted by CD8+ T cells in ICI myocarditis." (PMID 39023770, 2025). "MYH6 has previously been shown to function as an autoantigen in myocarditis, and autoantibodies against MYH6 have been observed in patients hospitalized with COVID-19." (PMID 36670100, 2023). "For example: MYH6 is suggested to be targeted on CD4+ T cell in a spontaneous mouse model of myocarditis." (PMID 37691828, 2023). "Transgenic expression of α-MYHC (such as MYH6) in thymic epithelium conferred tolerance to cardiac myosin and prevented myocarditis, demonstrating that α-MYHC is a primary autoantigen in mediating central and peripheral T cell tolerance." (PMID 37691828, 2023). "Our differential gene analysis did detect MYH7 and MYH6, and MYH6 was also among the hub genes of the severe myocarditis cohort." (PMID 36286305, 2022). "Nevertheless, many patients with MYH6-expressing tumors do not develop myocarditis after ICI therapy, thus suggesting that the mechanism may be more complex and that further risk factors may play a role." (PMID 39023770, 2025).
Arrhythmia (12 papers, 2015 to 2025). Any cardiac rhythm other than the normal sinus rhythm. "It has been reported that the mutation of MYH6 can lead to arrhythmia and sudden cardiac death in DCM." (PMID 38699233, 2024). "Mice expressing the human FHC-causing mutation R403Q in the myosin heavy chain gene (MYH6) recapitulate the human phenotype, including cytoskeletal disarray and increased arrhythmia susceptibility." (PMID 37438479, 2023). "The Myh6-McmTamDspfl/fl mice show severe cardiac dysfunction, cardiac arrhythmias, extensive myocardial fibrosis, and PANoptosis and die prematurely, typically within 4 to 6 weeks of age, as published." (PMID 40608429, 2025). "Genetic variants in both MYH6 and MYH7 have been linked to numerous human cardiac pathologies, including hereditary cardiomyopathies, arrhythmias, as well as CHD." (PMID 35621855, 2022). "Many groups have reported MYH6 variants in association with septal defects (most commonly ASD), as well as in various types of arrhythmias and sudden cardiac death." (PMID 35621855, 2022). "Only occasional ventricular ectopic beats, sinus brady-arrhythmias, and episodes of sinus pause were detected in Myh6-Cre:DspW/F mice." (PMID 34447973, 2021). "These electrical changes were coupled with altered cardiomyocyte calcium handling apparent in POAF atria prior to the onset of arrhythmia, as evidenced by changes in SLN, MYH6 and SERCA2a gene expression and reduced sarcolipin protein expression." (PMID 27390994, 2016). "Furthermore, downstream genes (MYH6, MYH7, TNNT2, NKX2-5, and CCND1) regulated by SFRP4 partake in ICM-related diseases like HF and arrhythmias." (PMID 40066352, 2025). "TBX5-targeted genes, MYH6, ACTC1 and TPM1, were involved in arrhythmia." (PMID 32423033, 2020). "We speculate that prolonged survival in the Myh6-McmTamDspfl/flMb21d1–/– mice was likely because of the beneficial effect of partial inhibition of the CDSP pathway on cardiac function and unlikely because of a reduced burden of cardiac arrhythmias." (PMID 40608429, 2025).
congenital heart disease (10 papers, 2007 to 2025). A heart disease that is present at birth. "The CADD based pathogenic ranking revealed a compound heterozygous mutation in MYH6 in a family with pleiotropic congenital heart disease." (PMID 27760138, 2016). "Myh6 was connected with congenital heart disease and implied that increasing mutation of Myh6 might be associated with congenital heart disease." (PMID 40271502, 2025). "MYH6 was associated with congenital heart disease, and indicate that by increase mutation of MYH6 could be associated with congenital heart disease." (PMID 32631246, 2020). "Our result indicates that this nonsense mutation (R1279X) in MYH6 might be the genetic cause of congenital heart disease." (PMID 29969989, 2018). "Together with findings of independent genomic investigations, MYH6 has emerged as a compelling disease gene for HLHS and other left-sided congenital heart diseases." (PMID 35448093, 2022). "A similar effect was observed in developing chicken atria upon knock-down repression of MYH6 using oligonucleotides complementary to MYH6 mRNA, suggesting that an altered MHC-α structure or lack of this protein contribute to congenital heart disease." (PMID 18159245, 2007).
sarcopenia (10 papers, 2019 to 2025). Progressive decline in muscle mass due to aging which results in decreased functional capacity of muscles. "Our results suggested that BDNF, JAK2, RhoC, Myh6, Stat5a, Tnnc1, and other genes may mediate the beneficial effects of exercise on sarcopenia through these pathways." (PMID 39309455, 2024). "Transcriptomic analysis identified BDNF, JAK2, RhoC, Myh6, Stat5a, and Tnnc1 as core target genes that may mediate the effects of different exercise intervention stimuli through the JAK-STAT, cGMP-PKG, and Rap1 pathways to improve the skeletal muscle phenotype of sarcopenia." (PMID 39309455, 2024).
atrial fibrillation (7 papers, 2018 to 2024). A disorder characterized by an electrocardiographic finding of a supraventricular arrhythmia characterized by the replacement of consistent P waves by rapid oscillations or fibrillatory waves that vary in size, shape and timing and are accompanied by an irregular ventricular response. "Previous reports on MYH6 rs28711516 (c.166G > A; p.G56R) associations with atrial fibrillation and sporadic dilated cardiomyopathy and a GWAS study from south India warrant further investigation of this gene." (PMID 37322441, 2023). "Analysis of the link between atrial cell differentiation and atrial fibrillation singled out known risk genes, such as MYH6 and FBXO32." (PMID 34194671, 2021). "Like p.Gln254Pro in MYZAP, the three low-frequency missense and frameshift variants we have previously reported to increase the risk of atrial fibrillation, in MYH6, MYL4, and PLEC, also increase the risk of SSS8." (PMID 30271950, 2018). "Furthermore, GWAS of multiple cardiac traits, such as atrial fibrillation and PR interval, identified loci associated with embryonic development-associated genes and genes whose mutations are known to cause serious heart defects, such as TTN, GATA4, MYH6, NKX2-5, PITX2, and TBX52–4." (PMID 36854752, 2023).
hypoplastic left heart syndrome (7 papers, 2016 to 2024). Hypoplastic left heart syndrome (HLHS) refers to the abnormal development of the left-sided cardiac structures, resulting in obstruction to blood flow from the left ventricular outflow tract. "The index case in Family 5 (Family 5, III-3) recessive for rare maternal and paternal MYH6 mutations (maternal:c.G5653A:p.E1885K/paternal: c.G1482A:p.M494I) died shortly after birth of hypoplastic left heart syndrome." (PMID 27760138, 2016). "Downregulation of Myh6 occurred concomitantly with a reduced ejection fraction of systemic right ventricular tissue in patients with hypoplastic left heart syndrome." (PMID 34395518, 2021).
Myocardial fibrosis (7 papers, 2015 to 2025). "The specific mechanism may be related to ventricular remodelling and myocardial fibrosis caused by MYH6, but further large‐scale experiments are needed to verify and elaborate on the specific mechanism." (PMID 34697898, 2021). "The Myh6-Cre-DspW/F mice in the untreated or placebo-treated groups exhibited cardiac dilatation and dysfunction, increased myocardial fibrosis, and apoptosis upon completion of the study, which was verified by complementary methods." (PMID 34447973, 2021).
sick sinus syndrome (7 papers, 2016 to 2023). A constellation of signs and symptoms which may include syncope, fatigue, dizziness, and alternating periods of bradycardia and atrial tachycardia, which is caused by sinoatrial node dysfunction. "The MYH6 p.R721T was associated with high risk of sick sinus syndrome." (PMID 33949037, 2021). "MYH6 gene mutations also lead to sick sinus syndrome in humans." (PMID 26815362, 2016). "Holm and colleagues found a close correlation between sick sinus syndrome (SSS) and MYH6 missense mutations." (PMID 37701139, 2023).